MSN (moesin)
Diseases named in the same sentence as MSN in open-access papers (continued):
Sharing a sentence is not in itself a finding about the gene and the disease.
glioma (continued). "Furthermore, to demonstrate the role of moesin in HA-induced cell migration, both glioma cell lines were transfected with moesin siRNA followed by treatment with HA (100 μg/mL) for 48 h." (PMID 23855374, 2013). "Glioma cells treated with TNFα positive control) also showed a strong band for moesin." (PMID 23855374, 2013). "Notably, glioma cells showing lower expression of moesin also showed reduced cell migration in wound-healing assays as compared to no transfection controls." (PMID 23855374, 2013). "Our results suggest that development of inhibitors which interfere with CD44-moesin interactions may provide a means to counteracting cellular migration in gliomas." (PMID 23855374, 2013). "Our results suggest that development of inhibitors which interfere with CD44-moesin interactions may open a new avenue in the future to mitigate cellular migration in gliomas." (PMID 23855374, 2013). "Notably, glioma cells transfected with moesin siRNA displayed reduced migration and invasion on treatment with hyaluronan (HA), an important component of the extracellular matrix in GBM." (PMID 23855374, 2013). "Four glioma antigens were identified, including FKBP prolyl isomerase 10 (FKBP10), glycogen phosphorylase L (PYGL), annexin A5 (ANXA5), and moesin (MSN), which were correlated with elevated APC infiltration and better prognoses." (PMID 40948290, 2025). "Similar to the expression pattern of CGGA mRNAseq-325, CGGA mRNAseq-693 and TCGA merged GBMLGG cohorts, CHI3L1, MSN and TIMP1 were expressed higher in high-grade gliomas than in low-grade gliomas." (PMID 35332109, 2022). "The amplified expressions of ANXA5, FKBP10, MSN, and PYGL were correlated with favorable prognosis OS and DFS of glioma, which exert pivotal roles in glioma development and progression." (PMID 34512630, 2021). "Previous findings indicated that HA can significantly enhance the invasiveness of glioma cells by promoting the binding of CD44 and Moesin." (PMID 33292278, 2020). "ERM (Ezrin, Radixin, and Moesin) proteins play an important role in cancer migration and invasion and interact with NKCC1 protein in glioma migration." (PMID 24555568, 2014). "This provided us the impetus to examine the role played by moesin, downstream of HA-CD44 signaling in glioma cells." (PMID 23855374, 2013). "To determine the expression levels of HA-receptor, CD44 and ERM protein, moesin, in NHA and glioma cell lines (U87 / U373), we carried out Western blot analysis." (PMID 23855374, 2013). "Four antigens ANXA5, FKBP10, MSN, and PYGL were promising to develop mRNA vaccine against glioma." (PMID 34512630, 2021). "Here, we reported that this pathway participated in TMZ-R glioma, and it could be disrupted by fasudil, leading to the dislocation of ABCG2 via suppression of p-moesin." (PMID 29416017, 2018). "Moesin was downstream of ROCK2 and regarded as a glioma progression marker." (PMID 29416017, 2018). "Similar results were observed in glioma cells transfected with siRNA targeting moesin followed by HA-treatment, in comparison to no transfections controls and cells transfected with scrambled siRNA when treated with HA." (PMID 23855374, 2013). "Western blot analysis showed no significant change in expression of either moesin or CD44 in glioma cells (U87 / U373) on treatment with HA." (PMID 23855374, 2013). "To determine whether these sTDEV populations include exosomes, we characterized sTDEV populations released by LL/2 Lewis lung carcinoma and F98 glioma cells after treatment with different doses of H-FIRE for exosomal markers (HSP70 and moesin) via Western blot." (PMID 41294835, 2025). "Notably, confocal laser scan microscopy revealed increase in membranous co-localization of both moesin and CD44 in HA-treated glioma cells in comparison to no treatment controls, suggesting HA-induced moesin-CD44 interaction in glioma cells may be responsible for increase in migratory cells." (PMID 23855374, 2013).
pancreatic cancer (14 papers, 2011 to 2025). "Overall, the proteomic studies revealed the association of radixin, moesin, c14orf166, S100P and hemopexin in LN metastasis in pancreatic cancer." (PMID 39195316, 2024). "Moreover, moesin-dependent cytoskeleton remodelling is associated with an anaplastic phenotype of pancreatic cancer." (PMID 33573274, 2021). "PAD2 isozyme-specific inhibitor had the strongest effects on reducing Panc-1 cell invasion capability, which was accompanied by an increase in moesin expression, which in pancreatic cancer is found to be reduced and associated with pancreatic cancer aggressiveness." (PMID 33573274, 2021). "Interestingly, in pancreatic cancer, moesin was found to be strongly downregulated and this was associated with cancer aggressiveness, albeit other studies have reported that moesin contributes to pathological state and may be linked to metastasis." (PMID 33573274, 2021). "Phosphorylation of moesin has been shown to be important for podosome rosette formation in Src-transformed fibroblasts; while in pancreatic cancer cells, ezrin regulates podosome organization independently of its activation." (PMID 41143651, 2025). "Based on these findings, increasing moesin expression should be anti-oncogenic in pancreatic cancer, and would align with elevated moesin protein levels observed particularly with PAD2 inhibitor treatment in Panc-1 cells in the current study." (PMID 33573274, 2021). "Moesin acts as a potential epithelial-mesenchymal transition (EMT) marker in breast and pancreatic cancer, and the expression level of moesin is linked to tumor size, invasion, and differentiation of oral squamous cell carcinoma." (PMID 25136657, 2014). "For example, MSN knockdown pancreatic cancer cells showed increased migration, invasion, metastasis and extracellular matrix organization, and EZR was found to be involved in the process of invasion of endometrial cancer cells." (PMID 21448288, 2011). "Moesin (MSN) belonging to ERM family of proteins has been shown to be associated with progression of different cancer types including papillary thyroid carcinomas, glioblastoma tumors, pancreatic cancers and colorectal carcinoma." (PMID 35642021, 2022). "In pancreatic cancer there are some contradictory findings regarding moesin expression." (PMID 33573274, 2021). "Consistently, silencing of CD44 by siRNA suppressed MSN-driven reduction in MTT-based viability of PANC1 and Pa03C pancreatic cancer cells." (PMID 37699930, 2023). "The elevated level of MSN in PI3K-activated MSC-derived CM was consistent with its tumor-suppressive actions on PANC1 and Pa03C pancreatic cancer cells." (PMID 37699930, 2023). "Consistent with the anti-tumor role of MSN, the application of recombinant MSN proteins downregulated K-Ras in PANC1 and Pa03C pancreatic cancer cells." (PMID 37699930, 2023). "On the other hand, moesin has been considered as a potential marker for epithelial-mesenchymal transition (EMT) in breast and pancreatic cancer and it has been reported to be strongly upregulated in breast and basal breast carcinomas." (PMID 27029001, 2016). "For instance, overexpression Moesin and Radixin are present in pancreatic cancers with lymph node metastases as compared with those where metastases are absent." (PMID 27746764, 2016).
melanoma (10 papers, 2011 to 2024). A malignant, usually aggressive tumor composed of atypical, neoplastic melanocytes. "MCAM-mediated activation of PI4K signalling was reported to help recruitment of actin-linking ezrin–radixin–moesin to cell protrusions and promote melanoma cell motility." (PMID 36291660, 2022). "Moesin controls the adhesion dependent activation of Rho and subsequent myosin II contractility during 3D collagen invasion by melanoma cells." (PMID 24392146, 2014). "MSN localizes to the trailing edge of invasive melanoma cells and disruption of this localization leads to decreased metastasis." (PMID 21501518, 2011). "Both MSN and MCAM are highly expressed in metastatic melanoma cells and known to regulate cell migration." (PMID 28923978, 2017). "In an effort to determine the exact molecular mechanism of CD146-stimulated migration of human melanoma cells, a recent study found that CD146 physically interacts with phosphorylated ezrin–radixin–moesin (p-ERM) proteins and recruits ERM proteins and the actin cytoskeleton to cell protrusions." (PMID 25685061, 2015). "In addition, with the exception of PAR1 and PAFR, moesin, but not ezrin, was also necessary for the metastasis of melanoma to the lungs; this protein, both physically interacts with and was recruited by CD146." (PMID 25685061, 2015).
prostate carcinoma (10 papers, 2009 to 2026). A carcinoma that arises from epithelial cells of the prostate gland. "Our results confirm data from earlier studies that were obtained in breast, lung, and prostate cancer cell lines, in that high expression levels of caveolin-1, caveolin-2, annexin-1, moesin, Eph2A, and uPA were associated with in vitro sensitivity to dasatinib." (PMID 19861960, 2009). "Collectively, we demonstrated herein the iTS cell-based approach to protect bone from prostate cancer and showed MSN as a potent extracellular tumor-suppressing protein." (PMID 41750310, 2026). "MSN and MSNP1 were in the same PGG family and hsa-miR-96 potentially regulates MSN in the TCGA prostate cancer dataset." (PMID 31029062, 2019). "In the non-type molecular subtype, TLN1 is significantly hyperphosphorylated at S425 in the head domain (band 4.1, ezrin, radixin, moesin homology domain), a site also known to be hyperphosphorylated in prostate cancer." (PMID 31108958, 2019). "Earlier reports have shown that high expression of annexin-1, caveolin-1, caveolin-2, moesin, and uPA, as well as low expression of IGFBP2, was associated with the in vitro response to dasatinib in breast, lung, and prostate cancer cells." (PMID 19861960, 2009). "Besides, there found that G protein-coupled receptor kinase GRK5 can phosphorylate moesin to promote prostate cancer metastasis and MiR-200 can promote cancer cell invasion through an unclear way which depended on moesin." (PMID 33838692, 2021). "Immunohistochemical staining of moesin in prostatic adenocarcinoma show significantly reduced staining intensity in Stage 4 compared to Stage 2 PCa, and further studies on the protein may help elucidate its role in prostate cancer progression." (PMID 23717685, 2013). "As a result, parent genes HTR7, CNN2, MSN, and TAGLN2 are DE; they generate pseudogenes, which are specifically expressed in prostate cancer samples." (PMID 31029062, 2019). "Ezrin and moesin expression was reduced in androgen-sensitive LNCaP and 22Rv1 prostate cancer cell lines compared to androgen-sensitive non-malignant PWR-1E prostate cells." (PMID 39858418, 2024). "While the expression levels of two members of this family, radixin and moesin, have been studied in many tumor types, to our knowledge they have not been investigated in prostate cancer." (PMID 21235778, 2011). "While moesin staining was higher in specimens of PCa than in normal tissue, the staining scores were also higher in HGPIN than they were in PCa, which makes moesin unlikely to be a useful clinical biomarker to diagnose prostate cancer based upon this study." (PMID 21235778, 2011).
glioblastoma (7 papers, 2010 to 2025). The most malignant astrocytic tumor (WHO grade IV). "Our results suggest several novel genetic alterations linked to glioblastoma multiforme progression and, more specifically, reveal Moesin as a novel glioblastoma multiforme-associated gene that has a strong survival effect and whose depletion in vitro significantly inhibited cell proliferation." (PMID 20822536, 2010). "In glioblastoma, increased MSN expression increased the expression of β-catenin, CD44, ICAM-1, and MMP-2.28." (PMID 37446127, 2023). "Increased MSN expression activates the Wnt/β-catenin pathway and results in aggressive orthotopic glioblastoma development in mice." (PMID 37446127, 2023). "Moesin is commonly overexpressed in high-grade glioblastoma, and its mode of action correlates with the CSC marker CD44." (PMID 36355541, 2022). "A previous study showed that MSN was frequently overexpressed in high‐grade glioblastoma, and MSN interacted and colocalized with CD44." (PMID 32941674, 2020). "Furthermore, the high expression level of MSN was correlated with the aggressive orthotopic growth of glioblastoma in nude mice." (PMID 37446127, 2023). "Furthermore, high MSN expression activated the Wnt/β-catenin pathway and resulted in aggressive orthotopic glioblastoma development in mice." (PMID 37446127, 2023). "Furthermore, moesin was shown to increase the expression of SOX2, promoting the functional transition of glioblastoma to an aggressive stem cell phenotype." (PMID 36355541, 2022). "The study identifies MSN as a key regulator of proneural‐to‐mesenchymal transition (PMT) in GSCs, driving resistance to radiotherapy (RT) and temozolomide (TMZ) in glioblastoma (GBM)." (PMID 39921260, 2025). "One member of the ERM family of proteins, moesin, was reported overexpressed in glioblastoma (GBM), but two other ERM proteins, ezrin and radixin, show no significant differential expression, and knockdown of moesin alone reduced the migration of GBM cells." (PMID 29416017, 2018).
Immunodeficiency (7 papers, 2018 to 2024). Failure of the immune system to protect the body adequately from infection, due to the absence or insufficiency of some component process or substance. "X-linked moesin-associated immunodeficiency (X-MAID) is a recently identified combined immunodeficiency caused by a mutation in the moesin (MSN) gene." (PMID 39781543, 2024). "Since mutations in the MSN gene are known to be associated with immunodeficiency, and since several episodes of recurrent infections occurred in both patients, we further investigated immune function abnormalities." (PMID 36119109, 2022). "We identified a hemizygous truncating variant in MSN (NM_001931.3:c.975G>A:p.(Lys352Asnfs*73)), which was proposed as a candidate gene for immunodeficiency based on a single publication." (PMID 34645488, 2021). "This mouse model provides novel insights into the mechanisms underlying moesin-based immunodeficiency." (PMID 35069520, 2021). "Unlike other actin regulatory proteins linked to immunodeficiency, moesin does not regulate actin filament growth." (PMID 35069520, 2021). "The immunodeficiency and inflammatory phenotypes that we observe in X-MAID mice differ dramatically from subtle abnormalities seen in mice bearing a germline deletion of moesin (MKO mice)." (PMID 35069520, 2021). "While X-MAID typically manifests in early life with symptoms of SCID, the MSN deletion may explain the immunodeficiency features observed here despite the absence of childhood symptoms." (PMID 39781543, 2024).
lung carcinoma (7 papers, 2011 to 2024). "GEPIA database was used to analyze the expression of MSN in different type tumors, the correlation between MSN expression and survival or prognosis of lung cancer." (PMID 37497401, 2023). "Higher expression of MSN is positively correlated with advanced lung cancer and suggests poor prognosis." (PMID 37497401, 2023). "These suggest that moesin regulates the expression of a variety of inflammation-related molecules to promote immune lymphatic infiltration and thus improves the prognosis of lung cancer patients." (PMID 33838692, 2021). "This fully proved that moesin can improve the prognosis of lung cancer patients by regulating a variety of inflammatory molecules." (PMID 33838692, 2021). "In order to have a profound exploration about the expression level of moesin in lung cancer, we first explore its expression status in nine lung carcinoma samples with the matched para-carcinoma tissue." (PMID 33838692, 2021). "Next, we explored the possible mechanism for high expression of moesin to improve the prognosis of lung cancer patients." (PMID 33838692, 2021). "Meanwhile, the protein and mRNA levels of MSN were highly expressed in lung cancer tissues." (PMID 37497401, 2023). "In addition, higher expression of MSN is positively correlated with advanced lung cancer, and higher expression of MSN suggests poor prognosis." (PMID 37497401, 2023). "Therefore, we found that moesin has a lower expression level in lung cancer than in para-carcinoma tissues." (PMID 33838692, 2021). "We recently showed that increased activity of the efflux transporter P-glycoprotein (P-gp) associated with activation of Snail transcriptional regulators may be mediated mainly by moesin in lung cancer cells." (PMID 34876945, 2021). "What is more, our results further showed that in lung cancer, moesin may not only promote the infiltration of NK cells." (PMID 33838692, 2021). "Moesin can enhance the infiltration of multiple immune lymphocytes in lung cancer." (PMID 33838692, 2021). "Whether the western blotting including its gray scale statistical results or qPCR indicated that both protein and mRNA of moesin is low-expressed in lung cancer tissue." (PMID 33838692, 2021). "Interestingly, our study showed that high expression of moesin is beneficial for lung cancer patients." (PMID 33838692, 2021). "Moesin is a poor expression in lung cancer tissues than the corresponding normal samples." (PMID 33838692, 2021). "However, moesin expression patterns can vary by cancer type, as moesin, like radixin, has been shown to be down regulated in cases of lung cancer." (PMID 21235778, 2011). "In addition, we detected the protein level of moesin in 82 pairs of lung carcinoma specimens and adjacent tissues, the results showed that moesin is mainly settled on the membrane, and obviously, the para-carcinoma has a higher level (43.9%, 36/82) than in the LUAD tissues (20%, 18/90)." (PMID 33838692, 2021). "As studies in recent years have shown that moesin has immune modulatory functions in immune cells and it is still unclear whether moesin has similar abilities in tumor cells, these prompted us to be interested in whether moesin expressed in lung cancer tumor cells could regulate anti-tumor immunity." (PMID 33838692, 2021). "In lung cancer cells, moesin levels were significantly increased with increase in P-gp activity which led to EMT implying a role for moesin in drug efflux." (PMID 33171868, 2020).